IGF1 (insulin like growth factor 1)
Diseases named in the same sentence as IGF1 in open-access papers (continued):
Sharing a sentence is not in itself a finding about the gene and the disease.
Obesity (918 papers, 2002 to 2026). Accumulation of substantial excess body fat. "Hyperinsulinemia, a hallmark of obesity-related metabolic dysfunction, enhances insulin-like growth factor 1 (IGF-1) signaling, further driving tumor growth." (PMID 40546611, 2025). "The IGF-1 signaling pathway is amplified in women with obesity and GDM and has been positively associated with macrosomia." (PMID 40362828, 2025). "The development and study of new molecules with dual, triple, or quadruple action targeting GLP-1, GIP, glucagon, and IGF-1 is important to cover as many pathogenic links of obesity with as few adverse effects as possible." (PMID 40649920, 2025). "When objectively examining these children, obesity was associated with height in 80% of cases against the background of elevated IGF-1 levels (25%) with normal growth hormone levels." (PMID 40370701, 2025). "Our current studies suggest that CUDC-907 reduces both tumor burden and serum IGF-1 levels in obesity-associated EC models." (PMID 41262902, 2025). "The combination of hyperinsulinemia and obesity was associated with significant decreases in (p = 0.0001) albumin, albumin/globulin, and IGF-1, and increases in LDH, NO, globulins (p = 0.006)." (PMID 40901060, 2025). "The development of diabetes in patients with acromegaly has been associated with a family history of diabetes, obesity, advanced age, and elevated IGF-1 levels." (PMID 40142714, 2025). "Second, Among obesity-related protein biomarkers, lower adiponectin levels and higher leptin and IGF-1 levels were associated with an increased BC risk." (PMID 40386557, 2025). "The influence of obesity on advanced BA is associated with factors such as BMI or total body fat mass, increased levels of estrogen, insulin-like growth factor-1 (IGF-1), etc." (PMID 41329658, 2025). "Hyperinsulinemia is also identified as a novel mechanism underlying tissue-level IGF1 resistance observed in human obesity and animal models of the disease." (PMID 40105689, 2025). "Insulin resistance, which is commonly associated with obesity, has been shown to promote prostate cancer by increasing circulating levels of bioactive IGF-1, a growth factor implicated in numerous types of cancer." (PMID 39941741, 2025). "Studies show that obesity can cause changes in baseline levels of insulin, insulin-like growth factor-1 (IGF-1), leptin, adiponectin, steroid hormones, and some cytokines." (PMID 39042663, 2024). "The insulin-like growth factor-1 (IGF-1) and insulin axes are upregulated in obesity and obesity-associated esophageal adenocarcinoma (EAC)." (PMID 39335147, 2024). "In contrast, obesity in puberty was linked to a reduction in growth velocity, a decrease in levels of IGF-1, as well as testosterone in boys and estradiol in girls." (PMID 39107621, 2024). "The results also accentuate circulating MEG3/miR-27a/IGF1/IGFBP3 as valuable markers of the early detection of obesity-related CRC, with miR-27a is associated with its risk." (PMID 38704452, 2024). "Instead, they developed obesity on a chow diet relative to wild-type mice, which was caused by the hypersecretion of insulin-like growth factor-1 (IGF1) and by increased lipogenic gene expression downstream of AKT and mTOR." (PMID 39136185, 2024). "As circulating biomarkers of obesity, C-peptide and IGF-1 were associated with the effects of exercise on these outcomes." (PMID 39822775, 2024). "Associations between obesity and cancer risk are explained with different suggestions, such as increased synthesis of bioavailable growth factors, insulin, and IGF-1 due to IR, synthesis of sex hormones, and chronic local inflammation." (PMID 38392069, 2024). "Further, an increased folds changes in mRNA expression of proapoptotic factors, antiapoptotic factors, PKC-δ, IGF-1, Akt, and Ki-67 was associated with obesity." (PMID 39395071, 2024). "In FM, a high prevalence (17.3%) of deficiency in growth hormone (GH)/insulin-like growth factor 1 (IGF1) signaling in obesity has also been described." (PMID 39273498, 2024).
Obesity (continued). "Increased IGF-1 levels can also lead to increased insulin sensitivity, which is strongly associated with obesity, as IGF-1 increases peripheral glucose uptake." (PMID 38540173, 2024). "Current evidence suggests that IGF-1 levels are associated with BMI whereby they are negatively related to obesity." (PMID 38987734, 2024). "Greater height in obese children aligns with evidence suggesting the earlier pubertal development and accelerated growth associated with obesity, which are likely due to hormonal imbalances, such as increased insulin-like growth factor (IGF-1)." (PMID 39771030, 2024). "Consider potential causes of falsely low IGF1 (malnutrition, liver disease, inflammation) and GH peaks (obesity, acute stress)." (PMID 39415786, 2024). "This study aimed to assess the IGF-1 levels in female patients with obesity, the change after surgery, and their association with the metabolic profile and weight loss after surgery." (PMID 38285303, 2024). "Obesity-associated free fatty acids (FFA) changes can lead to increased expression of insulin growth factor-1 (IGF-1) and diacylglycerol (DAG)." (PMID 39395071, 2024). "This increased growth is associated with higher plasma levels of IGF-1, which has been linked to a higher risk of obesity and IR later in life." (PMID 39599588, 2024). "Obesity is associated with alterations in circulating IGF1, IGF1-binding proteins (IGFBPs), insulin, inflammatory markers, and hormones implicated in cardiovascular disease, diabetes, cancer, and aging." (PMID 39458471, 2024). "Overall, obesity-associated endocrine deregulation marked by alterations in adiponectin, leptin, insulin, IGF1 and estrogens contributes to increased risk of cancer progression and recurrence in obese breast cancer patients." (PMID 39253073, 2024). "Further complicating the scenario is the association between obesity and declines in anabolic hormones, specifically insulin-like growth factor-1 (IGF-1), which plays a crucial role in muscle repair and growth." (PMID 38668557, 2024). "The present study aimed to assess the IGF-1 levels in female patients with obesity, the change after surgery, and the association between these levels, the patient’s metabolic profile, and weight loss after surgery." (PMID 38285303, 2024). "The insulin/IGF-1 axis has emerged as a pivotal mediator in the connection between obesity and the risk of diabetes." (PMID 38375323, 2024). "One possible cause is that they observed a higher serum Insulin-Like Growth Factor 1 (IGF-1) concentration in this group of infants, which is associated with a higher risk of obesity early in life." (PMID 38474864, 2024). "Various events are considered to elevate the risk of pancreatic cancer in obesity, such as the increase in IGF-1." (PMID 36755926, 2023). "While it is well established that IGF-1 levels are reduced in underweight children, evidence of the association between obesity and IGF-1 levels has been inconclusive." (PMID 37111069, 2023). "It should be remembered that IGF-1 belongs to obesity-associated adipokines, proteins that along with leptin, insulin and IL-6 are also produced by adipocytes." (PMID 36835075, 2023). "The aim of this study, therefore, was to explore associations between four genetic polymorphisms in the IGF1 axis in hypovitaminosis D-related obesity." (PMID 37892272, 2023). "It is worth noting that the decrease in IGF-1 levels caused by being underweight and obesity can be reversed by improving nutrition." (PMID 37111069, 2023). "IGF-1 plays an important role in obesity-associated endocrine-related cancers, promoting cancer development mainly through the PI3K/AKT and MAPK pathways." (PMID 36755926, 2023). "It has been suggested that deviations from normal GH and IGF-1 levels are linked with the development of obesity; however, the precise mechanisms underlying this relationship have yet to be fully elucidated." (PMID 37298507, 2023).
Obesity (continued). "In contrast, insulin-like growth factors-1 (IGF-1) can inhibit these physiological changes caused by obesity, and exerting a cognitive protective function." (PMID 37638322, 2023). "The association between obesity and tumorigenesis has been attributed to chronic low-grade inflammation, elevated levels of growth factors, insulin, and insulin-like growth factor-1." (PMID 37777736, 2023). "As such, the results suggest that participants carrying genotypes associated with elevated circulating IGF1 are prone to developing hypovitaminosis D-associated obesity." (PMID 37892272, 2023). "Obesity is associated with metabolic dysfunction and hyperinsulinemia, resulting in increased synthesis of insulin-like growth factor-1 (IGF-1), which activates the PI3K and MAPK signaling pathways, leading to cancer cell proliferation and survival." (PMID 37173991, 2023). "Ferritin, IGF-1, and liver steatosis account for the increased risk of poor prognosis in COVID-19 patients with obesity." (PMID 36851702, 2023). "The insulin/IGF-1 axis is associated with obesity-induced prostate carcinogenesis via the phosphatidylinostitol-3 kinase (PI3K)/Akt/mTOR pathways." (PMID 36755926, 2023). "Obese patients have lower IGF-1 during adulthood and obesity has a weaker association with IGFBP-3 compared with IGF-1." (PMID 37510722, 2023). "Studies have shown that short stature children were prone to complications from nutritional metabolic disorders such as malnutrition and obesity, which were associated with IGF-1 and IGFBP-3." (PMID 35180848, 2022). "Low muscle mass and obesity are also associated with several inflammatory cytokines, including interleukin-6, serum insulin-like growth factor-1, and hs-CRP." (PMID 36292469, 2022). "Along with the increase in obese patients, the association of IGF-1 levels with obesity has been attracting attention." (PMID 36418379, 2022). "Impairment of the GH/IGF-1 axis appears to be associated with the risk of developing sarcopenic obesity and ectopic fat deposition in the liver." (PMID 35954264, 2022). "Although plasma IGF-1 concentrations vary among individuals, including humans with obesity, overall, plasma IGF-1 concentrations are associated inversely with body mass index." (PMID 35350688, 2022). "IGF-1 secretion decreases with age in men approximately 60 years and older, which is associated with sarcopenia, muscle weakness, and upper extremity obesity." (PMID 35250869, 2022). "The TBC1D1-Ser231 KI mutation in mice gives rise to obesity and type 2 diabetes through promoting IGF1 secretion and thereby increasing lipogenesis in the adipose tissue." (PMID 35061665, 2022). "Among the most important proposed mechanisms linking obesity and cancer are obesity-induced low-grade inflammation and obesity-associated dysfunction of insulin/IGF1 signaling." (PMID 36320063, 2022). "Our previous study demonstrated that disruption of the AMPK-TBC1D1 axis increases lipogenesis in the adipose tissue and causes obesity and type 2 diabetes by promoting IGF1 vesicle secretion in a TBC1D1S231A-knock-in (KI) mouse model from 2 to 10 months." (PMID 35061665, 2022). "In this way, it is possible to highlight the mechanisms of action of leptin, resistin, adiponectin, aromatase, IGF-1, and pro-inflammatory cytokines in cancers to characterize new associations between obesity and other neoplasias." (PMID 36262532, 2022). "Disruption of the AMPK-TBC1D1 signaling nexus in a mouse model enhances lipogenesis in adipose tissue and subsequently causes obesity and type 2 diabetes by promoting insulin-like growth factor 1 (IGF1) secretion." (PMID 35061665, 2022). "The associated increase in IGF-1 and its signaling in obesity and DM is inversely linked with the survival of epithelial ovarian cancer." (PMID 34751020, 2022). "Laron syndrome is associated with insensitivity to GH and results in obesity and very low levels of IGF-1 in serum." (PMID 33816477, 2021).
Obesity (continued). "The role of insulin/IGF-1 signaling pathways in maintaining a differentiated phenotype of pancreatic islet β-cells and the development of obesity-associated DM II is discussed." (PMID 34208601, 2021). "GH serum levels in children with obesity tend to be reduced, while the association of obesity with IGF-1 is inconsistent and seems to be related to age." (PMID 34386750, 2021). "Obesity is associated with an imbalance of endocrine hormone signaling, especially impairments in insulin/IGF-1 pathway, decrease of adiponectin signaling, and leptin over-secretion and resistance." (PMID 33827616, 2021). "Other CAA-released growth factors and cytokines, including tumor necrosis factor (TNF)-α, IL-6, and insulin-like growth factor (IGF)-1, are implicated in the progression of obesity-related cancers, as well as adipokines and other lipid metabolites." (PMID 33572982, 2021). "One of them included higher levels of endogenous estradiol, while the other was associated with obesity, hyperinsulinemia and free IGF-1 levels." (PMID 34208601, 2021). "Obesity is associated with high concentrations of circulating insulin and IGF-1 secreted from the pancreas and hepatic tissue." (PMID 33827616, 2021). "Obesity and myeloma share signaling pathways that upregulate insulin, IGF-1, leptin, and inflammatory cytokines, raising the risk of malignant transformation." (PMID 33531904, 2021). "While inconsistent with truncated growth, elevated igf1/igf2 levels have been linked to obesity and attenuation of lipolysis." (PMID 34673019, 2021). "Obesity is also associated with elevated levels of local gut IGF-1 secreted from the mesenchymal cells around the ISCs." (PMID 33827616, 2021). "Obesity can cause changes in the levels of insulin, IGF-1, leptin, adiponectin, steroid hormones and cytokines in the body, creating a favorable environment for the occurrence and development of tumors." (PMID 35083251, 2021). "In the obesity group, serum P was associated with the Cu/Zn and Zn/Cu ratios, and IGF-1 with serum P was associated with serum Cu." (PMID 34684579, 2021). "Obesity has been attributed to 15–20% of cancer-related deaths where obese individuals often present with higher levels of IGF-1 which has been identified as a potential mechanism associating obesity with increased cancer risk and disease progression." (PMID 34684421, 2021). "To address what kind of obesity-associated factors reduced the anticancer efficacy of AdipoRon, we examined the effect of glucose, insulin, IGF-1 and leptin on the survival of AdipoRon-treated Panc02-Luc-ZsGreen cells in vitro." (PMID 33536560, 2021). "In the obesity group, serum P was associated with Cu/Zn and Zn/Cu ratios, and IGF-1 with serum P was associated with serum Cu." (PMID 34684579, 2021). "In fact, the 16–20% of BC patients are affected by metabolic disorders associated with aberrant IGF-1 signaling, like obesity and type-2 diabetes." (PMID 33557316, 2021). "The GH/IGF-1-axis is more or less restored after gastric bypass surgery implying that weight loss potentially improves the impaired GH/IGF-1 axis seen in obesity." (PMID 32860128, 2020). "Obesity is well-known to be associated with elevated circulating levels of insulin, insulin-like growth factor 1 (IGF-1), leptin, and inflammation." (PMID 32454823, 2020). "For instance, obesity is associated with a low-grade chronic inflammatory state, characterized by increased production of inflammatory mediators, together with enhanced IGF-1 and insulin signaling." (PMID 33364239, 2020). "We have found that the variation of the increased indices of inflammation such as CRP highly inversely associates with IGF-1 in obesity." (PMID 32806629, 2020). "The present results suggest that the reduced GH found in obese subjects is not due to a feedback inhibition by elevated IGF-1, since extreme obesity is associated with a decline in IGF-1 values." (PMID 32806629, 2020).
Obesity (continued). "As alluded to above, individuals with high circulating IGF1 levels, as well as those with insulin resistance and/or obesity, are at increased risk for several types of cancer." (PMID 33182502, 2020). "Recent studies have also confirmed that the abnormalities of the growth hormone/insulin-like growth factor 1 axis were associated with cardiovascular complications in people with obesity." (PMID 32149088, 2020). "Obesity is associated with significant metabolic and endocrine abnormalities, including increased blood levels of growth factors such as insulin, insulin-like growth factor-1 (IGF-1) and leptin that can promote tumor cell growth and survival." (PMID 32549336, 2020). "Three possible mechanisms are proposed to help explain the association between obesity and the increased risk of PC: the insulin / insulin-like growth factor-1 (IGF-1) axis, sex hormones and adipokines signaling." (PMID 30648824, 2019). "Some obesity candidate genes, such as genes encoding for the glucocorticoid receptor and insulin-like growth factor 1, have been found to be clustered in chromosomal regions associated with asthma." (PMID 30949213, 2019). "A possible mechanism on the involvement of body fat on CRC risk is based on obesity-related hormone levels, such as insulin, estrogens, and IGF-1, promoting carcinogenesis and counteracting apoptotic cell death." (PMID 31207998, 2019). "Obesity is a pathological state associated with dysregulated inflammatory and metabolic mediators, including blood glucose, insulin, IGF-1, and leptin." (PMID 31835454, 2019). "Obesity is associated with reduced spontaneous and stimulated growth hormone (GH) secretion and basal insulin-like growth factor I (IGF-1) levels—which in turn is associated with increased prevalence of cardiovascular risk factors." (PMID 31527400, 2019). "Chronic hyperinsulinaemia associated with obesity increases the bio-active levels of IGF-1 (insulin-like growth factor 1), which can promote tumour growth." (PMID 31752704, 2019). "In fact, the genomic region harboring the IGF1 locus was linked to size and lifespan across different breeds and serum IGF1 levels were shown to correlate with age and obesity in individual dogs." (PMID 31681409, 2019). "Obesity is associated with higher circulating levels of IGF-1, which is known to suppress apoptosis and stimulate tumour growth." (PMID 30670737, 2019). "Obesity, specifically abdominal obesity, appears to be associated with a decrease in free IGF-1 levels." (PMID 31608009, 2019). "IGF1 has been reported to relate to be associated with the cancer susceptibility, especially cancers caused by obesity, due to its important role in cell proliferation." (PMID 30111277, 2018). "Excess adipose tissue (overweight/obesity) is also associated with increased secretion of insulin-like growth factor-1 (IGF-1) in breast, colon, lung and prostate cancer patients." (PMID 30619088, 2018). "Obesity leads to higher levels of circulating insulin and IGF-1 in the body, which have been associated with risk for ER+ tumors and increased mammographic density in women with BMIs < 25 kg/m2, but not in overweight and obese women." (PMID 29804217, 2018). "Some studies have demonstrated that obese children exhibit the highest levels of serum IGF-1 and also exhibit a positive relationship between IGF-1 and adiposity, which perhaps contributes to their increased risk of obesity-related cancers." (PMID 29558911, 2018). "Apart from the common obesity-related co-morbidities, obesity is also associated with the abnormalities in the growth hormone (GH)- insulin-like growth factor 1 (IGF-1) axis." (PMID 29615058, 2018). "The data revealed that risk allele carriers have lower IGF-1 concentrations which can lead to obesity." (PMID 28913579, 2018).